RNF43 (ring finger protein 43)
Diseases named in the same sentence as RNF43 in open-access papers (continued):
Sharing a sentence is not in itself a finding about the gene and the disease.
cancer (continued). "Third, due to the varied expression of RNF43 in different cancer cell lines, whether downregulation of RNF43 in highly expressed GC cell lines would render stemness to these cancer cells remains unclear, and needs more study to elucidate." (PMID 28446252, 2017). "For example, a search of the P/PA databases for LGK974, a potent inhibitor of the Wnt secretion protein Porcupine identified by researchers at Novartis only turned up in PA by Novartis (PA# 20150125857 “Cancer Patient Selection for administration of Wnt Signaling inhibitors using RNF43 status”)." (PMID 27598201, 2016). "The novel combination of Porcupine and MEK inhibition synergistically inhibited RKO cell growth by more than 90%, which suggests this may be a promising therapeutic strategy to treat BRAF / RNF43 / ZNRF3 mutant serrated pathway cancers." (PMID 27661107, 2016). "Cytoplasmic RNF43 expression was least frequently observed in the BRAF mutant/MSI cancers." (PMID 27661107, 2016). "Our understanding of the R-spondin-ZNRF3/RNF43 signaling module in cancer is still evolving." (PMID 27338477, 2016). "Indeed, mutations of RNF43/ZNRF3 and recurrent translocations of RSPO2/RSPO3 have recently been identified in various cancers." (PMID 27338477, 2016). "The most common type of RNF43 mutation was a frameshift at nucleotide 659 (G7 repeat tract) in exon 9 that occurred in 43/54 (79.6%) BRAF mutant/MSI, in 1/33 (3.0%) BRAF mutant/MSS and 0/79 BRAF wild type cancers." (PMID 27661107, 2016). "We hypothesized that in serrated pathway cancers where APC mutation is uncommon, inactivation of RNF43 and/or ZNRF3 would present an alternate mechanism for activating the Wnt signal." (PMID 27661107, 2016). "Heterozygous loss of the RNF43 and ZNRF3 loci were identified in BRAF mutant/MSS cancers." (PMID 27661107, 2016). "The Cancer Genome Atlas Network in 2012 reported Wnt/β-catenin pathway mutations in up to 93% of colorectal cancers, and that was prior to the identification of RPSO2/3 translocations and RNF43/ZNRF3 mutations in the Wnt pathway." (PMID 25208913, 2014). "Previously reported genetic and cancer-associated mutations further corroborate the functional significance of the ZNRF3ecto–Rspo2Fu1–Fu2 interface as the generic interaction mode for Rspo1–4 and ZNRF3/RNF43." (PMID 24225776, 2013). "Our results reveal a novel negative regulatory mechanism of Wnt signaling at the receptor level and illuminate the mechanism by which RSPO-ZNRF3/RNF43 regulates Wnt signaling in human cells, which may provide new insights into regenerative medicine and cancer therapy." (PMID 41070826, 2025). "Thus, atypical BRAF mutations do not seem to follow the serrated/MSI/CIMP/RNF43 pathway of colorectal tumorigenesis but instead resemble cancers following the canonical pathway of colorectal tumorigenesis." (PMID 39751654, 2025). "Therefore, our study focused on elucidating ZNRF3/RNF43-regulated signaling pathways in cancer." (PMID 38260423, 2024). "Thus, it should be considered whether RNF43 should be included in multigene cancer panels, and if LPVs/PVs in RNF43 should lead to colonoscopy surveillance in SPS and CRC naïve families." (PMID 39546056, 2024). "Furthermore, RNF43 expression was significantly correlated with the efficacy of anti-PD-1/PD-L1 treatment, and it could predict the sensitivity of various anti-cancer drugs." (PMID 37848933, 2023). "In addition, the putative copy-number alterations of RNF43 from genomic identification of significant targets in cancer (GISTIC) included many types, such as gain function, diploid, and shallow deletion as displayed, which subsequently contributed to the changes of RNF43 expression." (PMID 37848933, 2023).
cancer (continued). "Besides, we further elucidated the predictive value of RNF43 for the immunotherapy efficacy and drug sensitivity in pan-cancer, thus highlighting the promising role of RNF43 as a clinical biomarker and a novel therapeutic target for cancer patients in clinic settings." (PMID 37848933, 2023). "Overall, our findings suggested that RNF43 was associated with OS in UVM, KIRC, and ESCA, associated with DFS in STAD, associated with DSS in KIRC and UVM, associated with PFS in KIRC, UVM, KIRP, and LIHC, confirming the potential role of RNF43 as a promising prognostic biomarker in human cancers." (PMID 37848933, 2023). "Also, RNF43 may participate in the regulation of immune response, immune system function, and immune cell infiltration during cancer development." (PMID 37848933, 2023). "Previous studies have indicated that RNF43 participates in mediating targeted therapy resistance and chemoresistance in several cancers, which may serve as a novel therapeutic target for overcoming drug resistance in cancer management." (PMID 37848933, 2023). "The results confirmed that RNF43 expression was significantly correlated with the sensitivity of several anti-cancer agents, such as cisplatin, fluorouracil, and lenvatinib, suggesting the potential of RNF43 in predicting the chemotherapy and targeted therapy responses in cancer patients." (PMID 37848933, 2023). "Besides, dynamic monitoring of RNF43 expression may be an effective approach to evaluate the responses of cancer patients to anti-cancer drugs, thus helping develop personalized treatment strategies for individual cancer patients." (PMID 37848933, 2023). "Next, we explored whether RNF43 could predict immune phenotypes in human cancers." (PMID 37848933, 2023). "Mutations in RNF43 were a particularly striking finding in these cases, as some noninvasive components contained several different RNF43 mutations, each limited to a small number of sections and none involving the invasive cancer." (PMID 32796935, 2020). "In BRAF wild type cancers with nuclear β-catenin staining, 19/27 (70.4%) showed a concomitant increase in RNF43 cytoplasmic expression, which may represent a futile attempt to dampen the Wnt signal by RNF43-mediated degradation of the Frizzled receptor." (PMID 27661107, 2016). "However, not all the cancer types previously associated with downstream Wnt pathway mutations harbor RNF43/ZNRF3 mutations." (PMID 27338477, 2016). "Together, these data suggest ZNRF3 and RNF43 as novel E3 ubiquitin ligases of EGFR and establish the inactivation of ZNRF3/RNF43 as a driver of increased EGFR signaling, ultimately promoting cancer progression." (PMID 41960900, 2026). "It is confirmed that RNF43 ubiquitinates B‐RAF at K499 to promote proteasome‐dependent degradation, resulting in reduced MEK activity and proliferative ability in cancer cells." (PMID 38225722, 2024). "Our results demonstrate that RNF43 ubiquitinated B‐RAF in a phosphorylation‐dependent manner to suppress proliferation and colony formation in cancer cells." (PMID 38225722, 2024). "Together, these data highlight ZNRF3 and RNF43 as novel E3 ubiquitin ligases of EGFR and establish the inactivation of ZNRF3/RNF43 as a driver of increased EGFR signaling, ultimately promoting cancer progression." (PMID 38260423, 2024). "Overexpression of ZNRF3 reduces EGFR levels and suppresses cancer cell growth in vitro and in vivo, whereas knockout of ZNRF3/RNF43 stimulates cell growth and tumorigenesis through upregulated EGFR signaling." (PMID 38260423, 2024). "In conclusion, our study unveils a novel ZNRF3/RNF43-EGFR signaling axis in cancer and provides critical insights into RSPO-ZNRF3/RNF43 signaling during cancer progression." (PMID 38260423, 2024).
cancer (continued). "We found that the expression of RNF43 was significantly upregulated in several cancer types, such as COAD, LUAD, and STAD, while was significantly downregulated in some cancer types, including GBM, KIRP, and PCPG." (PMID 37848933, 2023). "In this present study, our findings indicated that the expression of RNF43 was related to several immune cells, such as dendritic cells, T cells CD4, T cells CD8, plasma cells, macrophages, and B cells in various cancer types." (PMID 37848933, 2023). "Our study confirmed that RNF43 expression is significantly correlated with MSI and TMB in several cancer types, such as CESC, LUSC, COAD, and DLBC." (PMID 37848933, 2023). "More studies are needed to characterise the role of RNF43/ZNRF3 in NAFLD development and cancer progression." (PMID 35039505, 2022). "And we argue that the prolific cholesterol pool in RNF43‐mutant PDAC sustains continuous Fzd5 maturation and Wnt/β‐catenin‐dependent cancer growth." (PMID 35975457, 2022). "Above all, these results proved that miR-181d-5p promotes cancer stemness and RCC progression by targeting RNF43 and activating Wnt/β-catenin signal in vivo." (PMID 36319622, 2022). "This analysis identified 11 potential cancer drivers in the WNT signaling cascade, three of which were identified by oncodriveCLUST (RNF43: p = 7.22 × 10−6, MEN1: p = 0.02, and GNG12: p = 0.012)." (PMID 32384699, 2020). "RNF43, ZNRF3, RSPO2 or RSPO3 alterations in breast, colorectal, gastric, pancreatic and other cancers activate the Wnt/β-catenin signaling." (PMID 29312609, 2017). "This study suggests inactivation of RNF43 and ZNRF3 is important in serrated tumorigenesis and has identified a potential therapeutic strategy for this cancer subtype." (PMID 27661107, 2016). "Immunohistochemical staining was performed to detect presence of RNF43 protein expression for 63 BRAF mutant/MSI, 37 BRAF mutant/MSS and 44 BRAF wild type cancers from the formalin fixed series." (PMID 27661107, 2016). "Analysis revealed significantly higher expression for both RNF43 and ZNRF3 in BRAF wild type compared to BRAF mutant cancers and normal colorectal mucosa samples (p<0.0001 for both genes)." (PMID 27661107, 2016). "RNF43 and ZNRF3 had lower transcript expression in BRAF mutant compared to BRAF wildtype cancers and less cytoplasmic protein expression in BRAF mutant/MSI compared to other subtypes." (PMID 27661107, 2016). "At the 17q22 RNF43 locus, BRAF mutant/MSS cancers had significantly more frequent deletion events (at 18/33, 54.5%) than BRAF wild type cancers (4/18, 22.2%; p=0.04)." (PMID 27661107, 2016). "Depletion of RNF43 in PANC‐1 and normal human pancreatic ductal epithelial (HPDE) cells increased the protein levels of B‐RAF and the activities of B‐RAF and MEK, suggesting that this regulatory mechanism exists in both cancer and normal cells." (PMID 38225722, 2024). "However, the extent to which ZNRF3 and RNF43 act on other substrates, apart from WNT receptors, to influence development and cancer has been unclear." (PMID 38260423, 2024). "RNF43 p.G659fs, the most frequently reported mutant in several cancers, is capable of enhancing cell growth independent of Wnt signaling." (PMID 39125653, 2024). "Understanding how ZNRF3/RNF43 regulates EGFR and the crosstalk between EGFR and WNT receptors may offer potential therapeutic targets for cancer treatment." (PMID 38260423, 2024). "RNF43, an E3 ubiquitin ligase that negatively regulates Wnt/frizzled (FZD) receptors by their ubiquitination, internalization, and degradation, controls a key pathway in cancer." (PMID 39125653, 2024). "By identifying ZNRF3/RNF43 as crucial regulators linking EGFR and WNT signaling at the membrane receptor level, our work reveals a novel mechanism of EGFR and WNT coactivation, which is commonly observed in human cancers." (PMID 38260423, 2024). "The results showed that the correlation between RNF43 and MSI was remarkable in 8 cancer types." (PMID 37848933, 2023).
cancer (continued). "Together with its ligand RSPO3, the LGR5 receptor promotes β-catenin signaling in cancer cells predominantly via membrane clearance of two endogenous negative regulators of β-catenin signaling: the transmembrane ubiquitin ligases ZNRF3 and RNF43." (PMID 37998393, 2023). "A significant expression difference of RNF43 was found in 33 types of cancer excluding those without normal tissue data." (PMID 37848933, 2023). "Therefore, we further investigated the relation of RNF43 expression with MSI and TMB in different cancers." (PMID 37848933, 2023). "BRAF mutant cancers did not upregulate RNF43 or ZNRF3 expression at the transcript or protein level, unlike the BRAF wild type cancers that attempt to mitigate the Wnt signal." (PMID 27661107, 2016). "Many of those more frequent in BRAFmut/MSS cancers, for example deletions at 6p25.1-6p21.33 and at specific loci on 17q where several Wnt regulatory genes reside (RNF43, AXIN2 and SOX9), have not commonly been associated with CRC." (PMID 24651849, 2014). "Indeed, we have examined several peptides derived from a variety of cancer-testis antigens that have the oncogenic activity, including KIF20A, DEPDC1, MPHOSPH1, URLC10(LY6K),TTK, KOC1(IMP3), CDCA1, RNF43, and TOMM34." (PMID 24237633, 2013). "Interestingly, upon the real-time qPCR analysis of three cancer differentially expressed secreted protein gene candidates, COL3A1, DLG3, and RNF43 identified in this study, higher cancer expression levels of these genes in multiple cancer types were verified." (PMID 23282184, 2012). "ZNRF3/RNF43 loss-mediated EGFR stabilization represents a novel mechanism of EGFR upregulation, explaining the elevated EGFR protein levels observed in many human cancers without EGFR gene amplification or overexpression." (PMID 38260423, 2024). "Interestingly, COAD was the cancer type where RNF43, CYP2S1 and LIF showed the highest expression, suggesting that these three genes’ cancer-specific functions might be attributed to their adjacent super-enhancers." (PMID 37207350, 2023). "We had previously identified three oncoantigens, RNF43 (ring finger protein 43), 34 kDa translocase of the outer mitochondrial membrane (TOMM34), and KOC1 (IMP-3; IGF-II mRNA binding protein 3), as targets for the development of cancer peptide vaccines for CRC." (PMID 24884643, 2014). "Therefore, our findings suggest that RNF43 expression may influence the cancer patients’ prognosis through the interaction with the infiltration of T cell CD4+ and T cell CD8+ and macrophage polarization during cancer progression." (PMID 37848933, 2023). "Here, we have shown that within cancers that bear BRAF mutation, the mutually exclusive nature of mutations in these genes remain, indicating that the mutual exclusivity is likely between APC and RNF43 mutations, rather than between BRAF mutations and APC mutations." (PMID 32384699, 2020). "Additionally, inhibiting the Rspo-Lgr module may not be effective for anti-cancer therapy, as we have previously found that oncogenic RNF43 does not require Rspo for the acceleration of Wnt signalling." (PMID 32934222, 2020).
adenocarcinoma (7 papers, 2018 to 2025). A common cancer characterized by the presence of malignant glandular cells. "RNF43 mutations were present in 7 cases (13%), particularly in 3 adenocarcinomas, 2 LAMNs and 2 HAMN." (PMID 33712927, 2021). "In contrast, some genes related to the “epithelial-mesenchymal transition (EMT) process” and the “stem cell properties”, including RNF43, CDH1, and SMAD4, as well as the related TGF-β signaling pathway have been observed more frequently altered in SRCC than in conventional adenocarcinoma (AC)." (PMID 34381313, 2021).
infection (6 papers, 2015 to 2024). The state of being infected such as from the introduction of a foreign agent such as serum, vaccine, antigenic substance or organism. "It showed a gradual decline in RNF43 protein expression with progression of infection reaching to its lowest levels at 48 h.p.i in the infected cells." (PMID 25996295, 2015). "To achieve the same, we transfected A549 cells with pCDNA3.1 (mock) and pCDNA3.1-RNF43-Flag-HA (RNF43-HA) plasmids followed by PR8 infection after 24 h." (PMID 25996295, 2015). "The cell lysates were harvested 24 h post infection (24 h.p.i) and subjected to co-immunoprecipitation with anti-RNF43 antibody." (PMID 25996295, 2015). "Macroscopically, we could detect lesions in the stomachs of Rnf43 mutant mice, especially in the corpus, which were aggravated upon infection." (PMID 30884828, 2019). "However, H. pylori infection did not further enhance STAT3 activation, suggesting that STAT3 signaling may be involved in the pathology observed in Rnf43 mutant mice already under basal conditions, and may favor enhanced pathology upon infection by crosstalk with other signaling pathways." (PMID 30884828, 2019).
colon (3 papers, 2020 to 2025). "Similarly, CGX1321, another porcupine inhibitor, demonstrated encouraging activity in patients with RSPO or RNF43-mutated gastrointestinal tumors." (PMID 40943055, 2025).
colorectal (1 paper, 2026). "This phenotype contrasts with the loss‐of‐function behaviour observed for RNF43 or RNF43 mutations, underscoring that distinct RNF ligases can exert opposite influences on colorectal tumorigenesis." (PMID 41457280, 2026).
RNF43 also shares sentences with these, for which no sentence is quoted: dysplasia (3 papers); non-small cell lung carcinoma (3); uterine corpus endometrial carcinoma (3); acinar cell carcinoma (1); acute promyelocytic leukemia (1); benign melanocytic skin nevus (1); brain tumors (1); cervical cancer (1); cervical squamous cell carcinoma (1); colon adenoma (1); colorectal signet ring cell carcinoma (1); cutaneous melanoma (1); developmental delay (1); diffuse large B-cell lymphoma (1); ductal adenocarcinoma (1); endocervical adenocarcinoma (1); esophagogastric adenocarcinoma (1); fatty liver disease (1); gastric adenoma (1); head and neck squamous cell carcinoma (1); hepatitis C (1); hyperplastic polyp (1); intrahepatic cholangiocarcinoma (1); iron deficiency anaemia (1); juvenile polyposis syndrome (1); kidney chromophobe (1); leukemia (1); liver diseases (1); liver fibrosis (1); lung squamous cell carcinoma (1).
A further 23 diseases each share a sentence with RNF43 in 1 paper.